CDHR3 (cadherin related family member 3)
Description:
Cadherins are calcium-dependent cell adhesion proteins. They preferentially interact with themselves in a homophilic manner in connecting cells; cadherins may thus contribute to the sorting of heterogeneous cell types. (Microbial infection) Acts as a receptor for human rhinovirus C.
Synonyms: CDH28; FLJ44366; FLJ23834
Tractability: Antibody: UniProt places it where antibodies can reach, with high confidence; its Gene Ontology location is reachable by antibodies, with high confidence; UniProt predicts a signal peptide or a membrane-spanning region.
Gene: Protein-coding gene on chromosome 7 (105,876,796 to 106,036,432, forward strand). Ensembl gene ENSG00000128536.
Subcellular location: Cell membrane
Gene Ontology:
Molecular function: protein binding; beta-catenin binding; cadherin binding; calcium ion binding
Biological process: adherens junction organization; calcium-dependent cell-cell adhesion; cell migration; cell morphogenesis; cell-cell adhesion mediated by cadherin; cell-cell junction assembly; cell-cell adhesion; homophilic cell-cell adhesion
Cellular component: plasma membrane; adherens junction; catenin complex; membrane
Genetic constraint (gnomAD): Loss-of-function variants: 66 observed, 74.5 expected, observed/expected ratio (o/e) 0.89, 90% interval 0.73 to 1.09. The upper end of that interval is the gene's LOEUF score, 1.09, which puts it in group 4 of 6, group 1 being the genes least tolerant of losing a copy. Missense variants: 976 observed, 1,035.8 expected, observed/expected ratio (o/e) 0.94, 90% interval 0.89 to 0.99. Synonymous variants: 381 observed, 391.59 expected, observed/expected ratio (o/e) 0.97, 90% interval 0.89 to 1.06.
Homologues: Orthologues: chimpanzee CDHR3 (99% identical), pig CDHR3 (80% identical), dog CDHR3 (78% identical), rabbit CDHR3 (78% identical), guinea pig CDHR3 (78% identical), rat Cdhr3 (73% identical), macaque CDHR3 (72% identical), mouse Cdhr3 (72% identical). Paralogues in human: DCHS1 (22% identical), CDH23 (21% identical), DCHS2 (20% identical), CDH2 (20% identical), CDH10 (20% identical), CDH11 (20% identical), CDH18 (19% identical), CDH4 (19% identical), CDH7 (19% identical), CDH9 (19% identical), CDH12 (19% identical), CDH1 (19% identical), and 21 more.
Diseases named in the same sentence as CDHR3 in open-access papers:
CDHR3 is named in the same sentence as 28 diseases in open-access papers, as found by Europe PMC text mining. Sharing a sentence is not in itself a finding about the gene and the disease. The quoted sentences say what the papers report.
asthma (63 papers, 2015 to 2025). "Variants of rs6967330 on CDHR3, a receptor for human rhinovirus C, are recognized as risk factors for severe exacerbations in childhood asthma." (PMID 40687950, 2025). "In line with this, SNP rs6967330 is associated with an increased risk for childhood development of asthma, and the presence of tyrosine correlates with increased CDHR3 expression at the cell surface." (PMID 39205256, 2024). "It has been found that asthma exacerbation risk is associated with the CDHR3 carrying A allele at rs6967330 which changes cysteine 529 to tyrosine (C529- > Y529)." (PMID 39599822, 2024). "Rhinovirus C is a comparatively newly identified RV that binds to human cadherin related family member 3 (CDHR3) and is associated with severe asthma exacerbations." (PMID 39538325, 2024). "Multiple studies have linked the CDHR3 variant rs6967330 with the risk of asthma, and the variant has been associated with CDHR3 protein expression in the airway epithelial cells." (PMID 39299705, 2024). "A single-nucleotide polymorphism (SNP) in CDHR3, the RV-C receptor, is associated with greater risk of asthma hospitalizations in homozygous and heterozygous children." (PMID 36937308, 2023). "The rs6967330 A allele in CDHR3 that has been previously demonstrated to be an asthma-risk allele has also been associated with higher RV viral load, RV protein expression, and increased ciliogenesis in AECs." (PMID 37773065, 2023). "A single-nucleotide polymorphism (SNP) in CDHR3 (rs6967330) has been reported to increase the surface expression of CDHR3 and associate with severe exacerbations of asthma in children." (PMID 36967681, 2023). "Allele A of single-nucleotide polymorphism (SNP) CDHR3_rs6967330 upregulates epithelial expression of RV-C receptors which results in more severe asthma exacerbations in children." (PMID 37750685, 2023). "Genome-wide association studies have identified several risk alleles for early childhood asthma, particularly in the 17q21 locus and in the cadherin-related family member 3 (CDHR3) gene." (PMID 36967681, 2023). "Earlier studies conducted in children with increased risk for asthma have shown that allele A at CDHR3 rs6967330 is associated with an increased risk for ARIs, specifically for ARIs caused by RV species C." (PMID 36967681, 2023). "The asthma risk allele rs6967330-A on CDHR3 was related to the susceptibility to RV-C infection as the encoded variant Tyr529 was associated with higher surface expression of RV-C-specific receptor (6, –, 8)." (PMID 37750685, 2023). "Compared with the dominant rs6967330-G (Cys529), the asthma risk allele rs6967330-A (Tyr529) led to higher surface expression of transmembrane protein CDHR3, whereby increasing RV-C binding and replication." (PMID 37750685, 2023). "The asthma risk allele in CDHR3, coding for RV species C receptor, was associated with an increased rate of RV infections and a decreased risk of RSV infection." (PMID 36967681, 2023). "HRV-C, which is associated with severe acute asthma attacks more frequently than other rhinoviruses (reviewed in Reference 100), binds to CDHR3 (cadherin-3)." (PMID 35192447, 2022). "Individual comorbidities, such as asthma or a CDHR3 polymorphism, have to be considered, as well as infections with other pathogens." (PMID 36016451, 2022). "Subsequent investigation has associated the CDHR3 asthma risk allele with heightened risk of respiratory tract illness with RV-C, but not other viruses." (PMID 34995322, 2022). "A genome-wide association study of asthmatic children defined an association between asthma and a functional polymorphism in cadherin-related family member 3 (CDHR3)." (PMID 36077310, 2022). "There is also evidence that the cadherin-related family member 3 (CDHR3) expressed in airway epithelial cells is associated with exacerbation susceptibility in children with severe asthma." (PMID 36203653, 2022).
asthma (continued). "In this context, genome-wide association studies unraveled that the genetic susceptibility to develop asthma is partly related to barrier dysfunction, with identified polymorphisms in the cadherin-related family member 3 (CDHR3) gene." (PMID 34248677, 2021). "In a genome-wide association study, a risk variant in the gene cadherin related family member 3 (CDHR3) was found associated with asthma exacerbations in early childhood." (PMID 34201058, 2021). "The rs6967330 variant in CDHR3 gene was confirmed to be a risk factor for severe childhood asthma exacerbations, probably by increasing HRV-C infection (7.5-fold) and protein surface expression." (PMID 33925009, 2021). "GWAS was performed for blood samples of 1173 Danish children (2–6 years) with recurrent acute hospitalizations for asthma, and CDHR3 (SNP rs6967330; p.Cys529Tyr) has been identified as a susceptibility gene for early childhood asthma with severe exacerbations." (PMID 33133517, 2020). "After adjusting for confounding factors, the A allele of rs3847076 in CDHR3 was associated with increased susceptibility to asthma (OR = 1.407, 95% CI: 1.030–1.923)." (PMID 33213402, 2020). "The A allele of rs6967330 in CDHR3 increased the risk of wheezing and hospitalizations for childhood asthma in a Danish study." (PMID 33213402, 2020). "Another asthma risk gene, CDHR3, was discovered in a GWAS of childhood asthma with recurrent acute hospitalizations before 6 years of age." (PMID 31989228, 2020). "There are only a few studies describing the relationship between CDHR3 polymorphisms and asthma, and the results were inconsistent in different populations." (PMID 33213402, 2020). "Since asthma exacerbations are often caused by infections, it is possible that CDHR3 variations increase susceptibility to infections, and exacerbations, because of disrupted epithelial integrity." (PMID 33133517, 2020). "The A allele of rs3847076 in CDHR3 was associated with increased susceptibility to asthma under the additive model (P = 0.032, OR = 1.407, 95% CI: 1.030–1.923)." (PMID 33213402, 2020). "In conclusion, this study is the first to identify that the airway epithelium related genes EMSY and CDHR3 were associated with adult asthma susceptibility in the Chinese Han population." (PMID 33213402, 2020). "A single nucleotide polymorphism (rs6967330, encoding C529Y) in CDHR3 regulates the display density of CDHR3 on cell surfaces and is among the strongest known genetic correlates for childhood virus-induced asthma susceptibility." (PMID 30532249, 2018). "A single-nucleotide polymorphism in CDHR3 (rs6967330, C529Y) is associated with a 10-fold increase of RV-C binding and progeny yield and is a major risk factor for rhinovirus C infection and asthma." (PMID 29350142, 2018). "Of note, CDHR3, which is a known susceptibility gene for asthma exacerbations and a receptor for rhinovirus species C20,21, was a highly ranked coexpression hub (rank 19 out of 506 genes) within module “A”." (PMID 29367592, 2018). "The asthma-associated SNP (rs6967330) causes a nonsynonymous mutation (G>A; C529Y) in the fifth cadherin repeat of CDHR3, which affects cellular localization." (PMID 28583446, 2017). "Genome-wide association studies have identified CDHR3 (cadherin-related family member 3) gene as a novel susceptibility locus for early life childhood asthma with severe exacerbations." (PMID 26668064, 2015). "A genome-wide association study identifies cadherin related family member 3 (CDHR3) as a susceptibility locus for severe early childhood asthma exacerbation and CDHR3 can mediate RV-C entry into host cells, thereby causing wheezing diseases and exacerbation of asthma." (PMID 40636260, 2025). "Since they express more CDHR3 surface receptors on the airway epithelium when attached to Rhinovirus C, children having this risk genotype at the CDHR3 gene are therefore more vulnerable to Rhinovirus C infection, leading to more severe infections and exacerbations of asthma 31,34." (PMID 40104184, 2024).
asthma (continued). "Moreover, CDHR3 has been identified as a susceptibility gene for asthma, especially in young children." (PMID 38451292, 2024). "A C529Y mutation in CDHR3 has been shown to increase asthma susceptibility." (PMID 36937308, 2023). "In addition, a genome-wide association study identifies CDHR3 as a susceptibility locus for early childhood asthma with severe exacerbations." (PMID 37685567, 2023). "In addition to CDHR3 rs6967330, asthma risk alleles at the 17q21 locus seemed to be associated with an increased rate of all ARIs in the STEPS birth cohort." (PMID 36967681, 2023). "Genome wide association studies (GWAS) of asthma and subsequent confirmation studies have identified several risk alleles for early childhood asthma, particularly in cadherin-related family member 3 (CDHR3) gene and in the 17q21 locus." (PMID 36967681, 2023). "The asthma risk alleles in CDHR3, GSDMA, and GSDMB were associated with an increased rate of ARIs (for CDHR3, incidence rate ratio [IRR], 1.06; 95% confidence interval [CI], 1.01–1.12; P = .02), and risk allele in CDHR3 gene with rhinovirus infections (IRR, 1.10; 95% CI, 1.01–1.20, P = .03)." (PMID 36967681, 2023). "CDHR3 is another susceptibility locus for early childhood asthma with severe exacerbations." (PMID 35192447, 2022). "Notably, a non-synonymous single nucleotide polymorphism (SNP; rs6967330[A]) that yields stabilized CDHR3 protein expression at the cell surface is a causal variant for early childhood asthma with severe exacerbations." (PMID 34995322, 2022). "Considering that CDHR3 is a receptor that enables the binding and replication of RV-C, the link between CDHR3 and asthma risk might be mediated by RV-C infection." (PMID 36077310, 2022). "This virus also stands out from other viral factors due to its large diversity (about 170 genotypes), very effective replication, a tendency to create Th2-biased inflammatory environment and association with specific risk genes in people predisposed to asthma development (CDHR3)." (PMID 31989228, 2020). "Interestingly, the corresponding gene for CDHR3 has been linked to childhood asthma with severe asthma exacerbations." (PMID 31989228, 2020). "Furthermore, CDHR3 gene expression was associated with exacerbation in children asthma population from 2 to 6 years of ages." (PMID 29992143, 2018). "Of note, CDHR3 was selected for these validation studies, because although it is a susceptibility gene for severe asthma exacerbations and a receptor for Rhinovirus-C, its endogenous cellular role is unknown." (PMID 29367592, 2018). "CDHR3 was selected for these studies because it is a candidate susceptibility gene for asthma exacerbations, but its normal endogenous cellular function is unknown." (PMID 29367592, 2018). "Recent genome-wide association studies have uncovered a link between gene polymorphisms in several junctional proteins such as PCDH1 (Protocadherin 1 gene) and CDHR3 (encoding cadherin-related family member 3) with asthma, as well as increased risk for severe viral infections." (PMID 28759570, 2017). "The same study identified an eQTL SNP for CDHR3 (rs17152490) in bronchial epithelial cells, which is in linkage disequilibrium with the GWAS SNP (rs6967330, G>A; C529Y), suggesting cis-regulation of CDHR3 expression can also contribute to the asthma risk." (PMID 28583446, 2017). "As examples of this, the risk allele for susceptibility variants near ORMDL3 is significantly more common in cases with childhood onset asthma, while the association near CDHR3 might be specific to children with early onset and severe exacerbations." (PMID 29333270, 2017). "CDHR3 was originally identified as an asthma susceptibility gene linked to childhood exacerbation." (PMID 28583446, 2017).
asthma (continued). "Epithelial eQTL could detect more specific biomarkers for different phenotype of asthma, such as CDHR3 associated with asthma in children with severe exacerbation, and CST1, which can differentiate asthmatic with EIB from those with no EIB." (PMID 27658857, 2016). "Another genetic predisposition associated with Cadherin-related family member 3 (CDHR3), a receptor for RV-C that mediates RV-C binding and replication in airway epithelia, appears to influence the risk of early RV-C infection and subsequent development of asthma." (PMID 37112805, 2023). "Our findings suggest that the CDHR3 variant-related genetic risk for early life RV-induced wheezing and later RV-related asthma pathology may differ from each other, or alternatively, our study may have been underpowered to detect weak associations with these outcomes." (PMID 36967681, 2023). "Further investigations that integrate CDHR3 risk haplotype, epigenetic profile, resulting mRNA expression, RV-C infection, and clinical severity indices might help to identify genotype prediction model for asthma and RTI severity in paediatric patients." (PMID 37750685, 2023). "Finally, we tested the hypothesis that phenotypes defined using this approach have distinct genetic associates by investigating their associations with the known asthma loci (17q12–21 and CDHR3)." (PMID 35050846, 2022). "Notably, CDHR3 is a susceptibility locus for wheezing illness and early childhood asthma." (PMID 35287614, 2022). "Such assessments might be particularly important for understanding the genetic mechanisms of childhood asthma, as also indicated by findings related to CDHR3 gene variants, another susceptibility locus for early childhood asthma specifically conferring susceptibility to rhinovirus-C infections." (PMID 33328473, 2020). "Recently, an asthma-related cadherin-related family member 3 (CDHR3) gene variant was associated with greater RV-C receptor display on pulmonary cell surfaces of children and adults, and associated with higher susceptibility to severe virus-triggered asthma episodes." (PMID 31647831, 2019). "Furthermore, the asthma-risk genotype of CDHR3 conferred increased RV-C binding and replication." (PMID 28472984, 2017). "There were significant differences between clusters in GSDMA SNP rs4795408 (p = 0.04), CDHR3 SNP rs6967330 (p = 0.01) and ANAXA1 SNP rs116849664 (p = 0.04), with asthma risk alleles being overrepresented in C2 and C4." (PMID 40501205, 2025). "A genome‐wide study of early and severe childhood asthma pointed to a significant interaction between another known gene for asthma, CDHR3, and GSDMB." (PMID 40133993, 2025). "The lead variants of the CDHR3 and GSDMB loci showed significant associations with asthma and respiratory system–related phenotypes, assayed among the traits in the FinnGen DF10." (PMID 39299705, 2024). "Numerous asthma susceptibility genes, for instance, IL33, IL1RL1, MUC5AC, TSLP, CDHR3, and KIF3A, are expressed in the airway epithelium." (PMID 36832296, 2023). "Haplotypic analysis and GMDR should be included in identifying prediction models of CDHR3 for childhood asthma and RTIs." (PMID 37750685, 2023). "These were in loci previously associated with asthma exacerbations (GSDMB, RAD50, HLA‐DQB1, ADAM33, VDR, and CDHR3) or moderate‐to‐severe asthma (IKZF3, TSLP, MUC5AC, C11orf30, SMAD3, and WDR36)." (PMID 35754128, 2022). "In European‐descent populations, CDHR3, CTNNA3, and HLA‐DQB1 have been associated with severe asthma exacerbations." (PMID 35754128, 2022). "We found rs3847076 in CDHR3, rs2508746, rs1892953 and rs12278256 in EMSY were associated with the risk of adult asthma." (PMID 33213402, 2020). "This study was the first attempt to investigate the association between CDHR3, EMSY and adult asthma susceptibility in the Chinese Han population." (PMID 33213402, 2020).